EGFR (epidermal growth factor receptor)
Diseases named in the same sentence as EGFR in open-access papers (continued):
Sharing a sentence is not in itself a finding about the gene and the disease.
tumor (continued). "EGFR expression has also been shown to be more common in PB-type than in I-type ampullary adenocarcinoma and overexpression has been associated with shorter OS in I-type but not in PB-type tumours." (PMID 27070783, 2016). "In particular, Transtinib, irreversibly and selectively targets both sensitizing and resistant-L858R/T790M mutant EGFR with activity toward the interactive residues (Met790/793 and Cys797) of the nucleotide binding pocket, showing promising therapeutic responses in both tumor cells and mouse models." (PMID 26848869, 2016). "EGFR could be evaluated in 45/96 (46.9%) samples with normal squamous epithelium, 116/131 (88.5%) samples with normal gastric mucosa, 53/73 (72.6%) samples with intestinal metaplasia (IM), 170/174 (97.7%) primary tumours and 71/81 (87.7%) metastases." (PMID 26844548, 2016). "Although none of these tumor markers have been correlated with EGFR mutation status, CYFRA 21-1 has been shown to be useful in the prediction of TKI response in EGFR mutation patients, suggesting a potential correlation between CYFRA 21-1 and EGFR mutation status." (PMID 26979333, 2016). "Therefore one possibility is that additional genes on chromosome 7 that are co-amplified with EGFR may be involved in promoting a more aggressive tumor behavior." (PMID 27556186, 2016). "Typical alterations seen in IDHwt (primary) GBM such as EGFR amplification, chromosome 10 loss and homozygous deletion of CDKN2A were not present, although the observed gain of chromosome 7 and heterozygous deletion of 9p provide further evidence of the tumor’s astrocytic lineage." (PMID 26757882, 2016). "However, a pooled subset analysis from two randomised trials evidenced an advantage for dacomitinib over erlotinib, even if not statistically significant in EGFR mutation positive tumours." (PMID 27433281, 2016). "Similarly, EGFR overexpression was associated to hormone receptor negativity (P < 0.0001) and increasing tumor grade (P = 0.0008), but not tumor size (P = 0.2160)." (PMID 27484095, 2016). "Unfortunately, we could not determine the clinical relevance of these results because there are no clinical data on the frequency of the EGFR T790M mutation in drug-resistant tumor tissues." (PMID 27270313, 2016). "Activation of c-Met signaling and/or HGF up-regulation in the tumor microenvironment may confer resistance to RTKs-targeting cancer therapies already in clinical use, including epidermal growth factor receptor (EGFR) and v-RAF murine sarcoma viral oncogene homolog B1 (BRAF) kinase inhibitors." (PMID 27086914, 2016). "Therefore, we speculated that the superior survival of EGFR-TKIs therapy for patients with high quantities of EGFR mutations at baseline might be attributed to the presence of high percentage of EGFR mutant clones in the tumor entities." (PMID 26989078, 2016). "All of these genes have been associated with tumor growth and progression, and recent studies suggest that additional mutations in KRAS and NRAS, as well as downstream mutations in BRAF or PIK3CA, may cause resistance to anti-EGFR treatment." (PMID 26989027, 2016). "However, elevated level of the EGFR and/or its cognate ligands have been identified as common components of multiple cancer types, and appear to contribute to the transformation of cellular phenotypes, growth and survival of the tumor cells (reviewed in Ref." (PMID 30370422, 2016).
tumor (continued). "Epidermal growth factor receptor (EGFR) is a receptor tyrosine kinase, which is expressed on the cell surface to trigger downstream kinase signaling pathway via a ligand binding-mediated phosphorylation, and its auto-activation is correlated with tumor progression." (PMID 26497368, 2015). "Finally, we show that in GBM with EGFR amplification (EGFRamp), long-term exposure to erlotinib induces adaptive tumor growth that involves MET pathway activation, supporting the use of a combination of both inhibitors to more effectively control GBM progression." (PMID 26381735, 2015). "Consequently, the Akt protein can still be activated by other signals despite the EGFR blockage by h-R3, and this may lead to tumor progression." (PMID 26124180, 2015). "In vitro, EGFR inhibition or dual inhibition of EGFR and ErbB2 effectively suppressed cell growth and induced apoptosis in human and rodent biliary cancer cell lines and these inhibitors have also been shown to successfully block tumor growth in xenografted athymic nude mice." (PMID 26729094, 2015). "Classification of EGFR gene mutation status using the serum proteomic classifier established in the present study in patients with stage IIIB or IV NSCLC is feasible and may predict tumor response to EGFR-TKIs." (PMID 26047516, 2015). "EGFR activation induces many intracellular signaling pathways, such as the mitogen-activated protein kinase (MAPK), phosphatidylinositol 3-kinase (PI3K), and signal transducer and activator of transcription (STAT) pathways, which cause tumor cell proliferation and survival." (PMID 25532027, 2015). "Thus, drugs affecting tumor growth may involve factors that activate EGFR and factors that modulate EGFR trafficking from the plasma membrane to sites within the cell." (PMID 26132924, 2015). "In contrast, miR-139 expression was independent of tumor size or EGFR mutation." (PMID 26256448, 2015). "Because lymphocytes play an important role in tumor eradication and macrophages are associated with tumor progression, we presumed that patients with higher lymphocyte-to-monocyte ratio (LMR) might have better prognosis in EGFR-mutant NSCLC patients receiving first-line EGFR-TKIs." (PMID 26313661, 2015). "However, a possible mechanism is that the high-affinity allele V of V158F within FCGR3A might contribute to decreased ADCC-triggered by NK cell, but through cross-linking of the FCGR to increase activation of TAM in tumor microenvironment by anti-EGFR mAb." (PMID 26363448, 2015). "Finally, we compared MET- and EGFR-expression within these tumor tissues to investigate, whether a correlation exists between both biomarkers." (PMID 26215852, 2015). "Taking these findings in subtype specific context suggests that baseline pEGFR levels may make these tumours more prone to EGFR-mediated resistance suggesting the use of pEGFR as a predictive marker to identify patient populations who may respond to different combination therapy approaches." (PMID 26149458, 2015). "Therefore, EGFR is likely to affect multiple aspects of tumor growth and chemoresistance." (PMID 26491668, 2015). "Cetuximab may inhibit EGFR-dependent primary tumor growth and metastasis." (PMID 26294988, 2015). "Taken together, LZ8 may suppress EGFR signaling, thereby suppressing tumor progression of HCC329." (PMID 25607934, 2015). "In addition to EGFR activity, alternate signaling pathways may be stimulated in such tumors, underscoring the need for a more comprehensive analysis of tumor pathway circuitries in each patient." (PMID 26439803, 2015). "Consequently, their treatment regimens were changed and the EGFR T790M and PIK3CA mutations were no longer detectable in the tumor samples collected a couple of months later, and patients responded again to retreatment with an EGFR tyrosine kinase inhibitor." (PMID 25980577, 2015).
tumor (continued). "Based on our findings, NSCLC patients with lower EGFR/MET relative ratios, possibly reflecting a requirement for both signaling pathways to sustain tumor growth, may be the ideal patient subgroup to benefit from combined EGFR and MET inhibition compared to single agent therapy." (PMID 26439803, 2015). "Other gefitinib/erlotinib-sensitizing EGFR mutations, and more importantly, the T790M mutation, which can emerge during the treatment course with TKIs and then confer acquired drug resistance to the tumor cells, were not included." (PMID 25780439, 2015). "Furthermore, generating TKI-resistance in-vitro or in-vivo in EGFR mutant cancer cell lines engineered to have loss of RB expression did not yield resistant cells/tumours with acquisition of NE marker expression or SCLC morphology." (PMID 25758528, 2015). "Thus, the application of epidermal growth factor (EGF), which is one of several natural ligands for EGFR, could help cover all of the subsets of tumor cells that express wild-type EGFR, as well as its mutant forms." (PMID 28347118, 2015). "As the presence of tumor hypoxia may confer resistance to EGFR inhibitors, we performed growth inhibition experiments under normoxic and hypoxic conditions for the tyrosine kinase inhibitor erlotinib and the monoclonal antibody cetuximab on three human, cetuximab sensitive HNSCC cell lines." (PMID 26032726, 2015). "With regard to the hypothesis of a multi-targeted approach, another recent preclinical analysis demonstrated that adding chloroquine (acting as an autophagy inhibitor) to EGFR and AKT inhibition might potentially improve tumor responses in EGFR mutant NSCLC cells." (PMID 25904052, 2015). "For example, the expression level of epidermal growth factor receptor (EGFR) in CMCs affects clinical prognosis; HER-2 overexpression, occurring in about 20% of CMCs as in BC, or the loss of estrogen (ER) and progesterone (PR) receptors are related to tumor progression." (PMID 25884842, 2015). "Additionally, since the cetuximab and IMC-A12 treatments were limited to only three times at 3-d intervals, differential up-regulation of EGFR or IGF-1R after the termination of treatments may have contributed to accelerated tumor growth." (PMID 25355701, 2015). "Based on the hypothesis that tumor targeting is required for clinical benefit of anti-EGFR treatment, biodistribution and tumor uptake of 89Zr-cetuximab by Positron Emission Tomography (PET), combining the sensitivity of PET with the specificity of cetuximab for EGFR was evaluated." (PMID 26309164, 2015). "The tumour did not harbour either the EGFR or K-ras mutation." (PMID 25788996, 2015). "However, clinical trials targeting EGFR function have been so far disappointing since the heterogeneous distribution of EGFR throughout the tumor might render cells differentially sensitive towards EGFR inhibition, ultimately leading to therapy failure." (PMID 26136784, 2015). "A large study investigating mutation concordance within NSCLC primary tumours and between primary tumours and metastases or recurrences found no macroheterogeneity of EGFR driver mutations, further supporting the notion that activating EGFR mutations are generally truncal." (PMID 25555261, 2015). "If further analysis of clinical ear tumor specimens shows non-mutational activation of EGFR, it is possible that EGFR inhibitors that were ineffective in our preclinical studies such as erlotinib or cetuximab might be effective clinically." (PMID 26027747, 2015). "Furthermore, we found that EGFR levels tended to decrease in the residual tumors collected at surgery compared with the primary tumor before the commencement of therapy, indicating that the levels of EGFR may be influenced by the therapeutic pressure." (PMID 25887735, 2015). "Neither age nor tumor stage was significantly correlated with EGFR mutation." (PMID 25789627, 2015).
tumor (continued). "Approximately 30–50% of CRC tumours have a mutated KRAS gene, which indicates that up to 50% of the patients with this type of cancer could respond to therapy with antireceptor antibodies against the epidermal growth factor, EGFR." (PMID 25932044, 2015). "This has important implications for cancer therapy, as it could explain how chemotherapeutic agents such as cisplatin affect EGFR signalling, contributing to chemotherapy resistance and making tumours refractory to antibody therapies targeting the extracellular domain of EGFR." (PMID 26066081, 2015). "As just one example, hyperactivation of epidermal growth factor receptor (EGFR) signaling through receptor overexpression, or mutation of either the receptor or downstream signaling components, can lead to enhanced cell proliferation and motility, thereby contributing to tumor growth and metastasis." (PMID 25999952, 2015). "Furthermore, when taking the percentage of neoplastic cells in individual samples and the allelic frequency of the variants into account, in contrast to most mutations in KRAS, EGFR and BRAF, a large proportion of the newly identified mutations appear to be present in only a subset of tumor cells." (PMID 25637035, 2015). "Furthermore, tumor-derived spheroids from short-term cultures have been shown to initiate xenograft tumors that phenocopy the EGFR status of the original tumor in vivo, even when cultured in the presence of serum on agar-coated cell culture plates in order to avoid attachment." (PMID 26136784, 2015). "However, in this study, the information about type of tumor samples (primary or metastatic) used for EGFR mutation analysis was not provided." (PMID 25086987, 2015). "We then interrogated the EAM as to the behaviour of EGFR ubiquitination and phosphorylation over a range of receptor levels spanning from physiological levels (<105 EGFRs per cell) to the pathological levels detected in human tumours (>106 EGFRs per cell), at different EGF concentrations." (PMID 26264748, 2015). "The regressed tumours had significantly reduced ratio of pEGFR:EGFR (p<0.05) and pHER4:HER4 (p<0.001) compared to the tumours without regression, suggesting the inhibition on EGFR and HER4 might be the cause of tumour regression." (PMID 25691057, 2015). "By applying the same ‘exclusivity analysis’ to mutation data from other tumor types, however, we identified or confirmed other pairs of mutations—mutant KRAS and BRAF in COAD, mutant EGFR and NF1 in GBM, and mutant BRAF and NRAS in SKCM —that may be synthetically lethal in those tumors." (PMID 26047463, 2015). "Thus, research to identify active pathways downstream EGFR activation could lead the rationale for the development of multidrug combination therapies striking several critical points important to tumor development." (PMID 25784483, 2015). "Furthermore, based on the currently available data there is no outright preference for the use of either bevacizumab or anti-EGFR antibodies in combination with chemotherapy in patients with (K)RAS wild type tumours in whom secondary resection of metastases is the primary objective." (PMID 25943574, 2015). "However, enrichment was performed for tumour types likely to have high EGFR expression." (PMID 26659127, 2015). "In this regard, the found genetic portrait of cancer cells may mirror the underlying tumor heterogeneity, thus allowing to ultra-stratifying those EGFR mutant NSCLC patients, and estimating a differential clinical benefit of anti-EGFR TKIs in such already-selected subpopulation." (PMID 25904052, 2015). "Moreover, it is likely that other sub-clones of tumor cells will arise or other pathways may be upregulated as a mechanism of resistance to EGFR-targeted therapies." (PMID 25688333, 2015). "However, tumor response rates to second-line EGFR-TKIs are inconsistent." (PMID 26609535, 2015).
tumor (continued). "Moreover, immunohistochemical homogeneous expression of mut-EGFR suggests that they are generally driver mutations, being present all over the tumor without clonal diversification." (PMID 26422230, 2015). "A tumor sample obtained using only a single biopsy may not necessarily reflect the dominant properties of the tumor, and the primary activating EGFR mutation appears to represent the non-dominant tumor clone in patients with EGFR-TKI-resistant NSCLC." (PMID 26334838, 2015). "While many clinical trials investigating the combination of cetuximab with other agents have been designed on the premise that this agent exerts it’s anti-tumor effect via inhibition of signaling downstream of EGFR, many are also investigating the immune mediated effects that may occur." (PMID 26690220, 2015). "Thus, according to our findings, a broad spectrum of pathogens or molecules recognized by the PRRs could induce the EGFR signaling cascade through trigger IL-1β production, and such that the cascade exerts its tumor-promoting role." (PMID 26462152, 2015). "Therefore, we investigated whether the cooperative therapeutic effects of PI4KIIα and EGFR inhibition also exist for A549-induced tumor." (PMID 24801752, 2014). "In addition, the GCNs of EGFR in the tumor cells was found to differ markedly between patients." (PMID 25013472, 2014). "Thus, cross-talk between Notch and other signaling pathways may regulate tumor aggressiveness, including interactions with EGFR, which has been proposed as an upstream regulator of Notch through a non-autonomous cellular mechanism." (PMID 24945379, 2014). "Thus, we evaluated the effect of EGFR inhibition on the levels of EGFR protein in tumor cells." (PMID 25240937, 2014). "Thus, increasing microenvironmental stiffness broadly activates EGFR signaling in GBM tumor cells." (PMID 25000176, 2014). "However, analysis of the expression of EGFR and the presence of mutations requires a tumor biopsy, which is not possible to get in all situations." (PMID 24786689, 2014). "In addition to discussing indications and complications, we focus our discussion on diagnostic yields and the feasibility of testing for molecular biomarkers such as epidermal growth factor receptor and anaplastic lymphoma kinase, emphasizing the importance of a sufficient tumor biopsy." (PMID 25295226, 2014). "In particular, KRAS genotyping of primary tumor tissues or metastatic lesions is strongly recommended by the National Comprehensive Cancer Network (NCCN) Clinical Practice Guidelines in Oncology version 3 (2008) in patients with mCRC prior to any therapy that includes anti-EGFR mAbs." (PMID 24884535, 2014). "However, further studies assessing EGFR expression in tumor tissue should be performed to validate our hypothesis." (PMID 24516537, 2014). "Thus, we evaluated whether the negative effects of erlotinib in the T cell recognition of Sa-3 were mediated by immunosuppressive factors produced by the tumor cells as the result of EGFR inhibition." (PMID 25240937, 2014). "Overall, either type of tumor tissue, primary or secondary CRC (with a putative exception for metastatic lymph nodes), could be useful as a source to detect KRAS mutations in selecting patients to be addressed to anti-EGFR therapy." (PMID 25202344, 2014). "Additionally, to assess drug efficacy, tumour response to Gefitinib, an epidermal growth factor receptor (EGFR) tyrosine kinase inhibitor, was evaluated in mice injected with fluorescently labeled tumourigenic A549 cells and found to reduce tumour size over time." (PMID 25147799, 2014). "However it was still difficult to detect EGFR mutations in exhaled breath condensate because cellular components presented in exhaled breath condensate are not representative of the tumor." (PMID 25490772, 2014).